MMP2 (matrix metallopeptidase 2)
Diseases named in the same sentence as MMP2 in open-access papers (continued):
Sharing a sentence is not in itself a finding about the gene and the disease.
lung carcinoma (continued). "When the protein levels of MMP2 were measured, TGF-β induced the expression of MMP2 and Galunisertib reversed its level at three kinds of lung cancer cells." (PMID 34253166, 2021). "Studies in lung cancer metastasis also revealed the presence of a binding site of miR-29b at the MMP-2 3’UTR region through which it downregulates MMP-2 expression.miR-543 has been seen to be dysregulated in many cancers." (PMID 35145899, 2021). "The transcription of MMP2 was significantly increased by treatment with TGF-β in three lung cancer cells." (PMID 34253166, 2021). "Similar anti-cancer effects of fucoidan via the regulation of MMP-2 have also been reported in lung cancer cells." (PMID 33333858, 2020). "Increased MMP2 was displayed in lung cancer tissues at stages IIIA-IV (13/20, 65%) compared with those of stages IA-IIB (7/36, 19.4%) (p = 0.002)." (PMID 33115469, 2020). "First, the expression of MMP2 was increased in lung cancer tissues and increased MMP2 correlated with poorly differentiated cancer, tumor size, lymphatic metastasis and advanced TNM stage." (PMID 33115469, 2020). "e MMP2 expression in lung cancer tissues with N0-N1 of lymphnode metastasis was lower than that in those with N2-N3 of lymph node metastasis (p < 0.05)." (PMID 33115469, 2020). "f Increase of MMP2 was displayed in tissues with lung cancer at stages III-IV compared with those at stages I-II (p < 0.05)." (PMID 33115469, 2020). "d Expression of MMP2 in lung cancer tissues at T3–4 stage was significantly higher than that in T1–2 stage (p < 0.05)." (PMID 33115469, 2020). "c Upregulation of MMP2 was observed in poorly differentiated lung cancer tissues compared with well-differentiated tissues (p < 0.05)." (PMID 33115469, 2020). "Expression of MMP2 in lung cancer at T3–4 stage (12/19, 63.2%) was higher than that in lung cancer at T1–2 stage (8/37, 21.6%) (p = 0.032)." (PMID 33115469, 2020). "A study proposed that the silencing of ATF1 can induce the down-regulation of MMP2 expression, thereby inhibiting the migration and invasion of lung cancer cells." (PMID 33115469, 2020). "In IHC analysis, MMP2 was mainly expressed in cytoplasm and membrane of lung cancer cells and normal cells." (PMID 33115469, 2020). "a MMP2 was highly expressed in lung cancer tissues, whereas it was lowly expressed in matched adjacent non-malignant tissues (p < 0.05)." (PMID 33115469, 2020). "Matrix metalloproteinase 2 (MMP2) has been found to be related to malignant tumors; the aim of this study was to investigate the correlation between MMP2 expression in lung cancer tissues and clinical parameters of lung cancer." (PMID 33115469, 2020). "The correlation between the expression of MMP2 and clinical parameters of lung cancer was analyzed by Kaplan-Meier curve and multiple regression analysis." (PMID 33115469, 2020). "The pharmacological inhibition of FAK phosphorylation was linked to reduced MMP-2 and MMP-9 expression and activation in breast and lung cancer cells." (PMID 32545852, 2020). "High expression of MMP2 (p = 0.006) and advanced stage (p = 0.003) were independent prognostic indicators for survival of lung cancer patients." (PMID 33115469, 2020). "An increased level of expression and higher activity of MMP-2 is observed with increased vascularization of the metastases of lung cancer in the central nervous system." (PMID 33198257, 2020). "Further studies are needed to verify association of rs1799750 in MMP-1, rs243865 in MMP-2, rs11568818 in MMP-7, rs2252070 in MMP-13 and rs28366003 in MT2A with breast, colon and lung cancers." (PMID 32765800, 2020). "Through the COX regression analysis, we found that lung cancer patients with high-expression of MMP2 had a shorter survival time compared with those with low-expression." (PMID 33115469, 2020). "Expression of MMP2 in lung cancer with N2-N3 (18/33, 54.5%) of lymph node metastasis was up-regulated compared with that in lung cancer with N0-N1 (2/23, 8.7%) (p < 0.001)." (PMID 33115469, 2020).
lung carcinoma (continued). "Moreover, highly expressed MMP2 is an independent risk factor for poor prognosis of lung cancer patients, suggesting that MMP2 could be a useful diagnostic, prognostic, and predictive biomarker of lung cancer." (PMID 33115469, 2020). "Our findings are consistent with previous reports that MMP2 is highly expressed in lung cancer tissues and lowly expressed in normal tissues." (PMID 33115469, 2020). "By testing the expression level of MMP2 in lung cancer tissues, we analyzed the correlation between the MMP2 and the biological behavior of lung cancer." (PMID 33115469, 2020). "Our study showed that increased MMP2 significantly correlated with the malignant features of lung cancer such as tumor size, invasion and metastasis of lymph nodes, low differentiation and advanced stage." (PMID 33115469, 2020). "We also found that increased MMP2 in lung cancer tissues correlated with lymph node metastasis and advanced TNM stage." (PMID 33115469, 2020). "This study detected the expression of MMP2 in lung cancer tissues and analyzed the correlation between its expression level and the clinical characteristics of lung cancer." (PMID 33115469, 2020). "TLR4-induced autophagy activation promoted migration and invasion of lung cancer by induction of chemokines and immunosuppressive factors, such as IL-6, MMP2, and CCL2." (PMID 33172060, 2020). "A study focusing on lung cancer also reported that extracts of Antrodia cinnamomea decreased expression of MMP-2 and MMP-9 as well as their activities, which was ascribed to dysregulation of ERK, JNK, p38, and PI3K/Akt signaling pathways." (PMID 32401928, 2020). "It was previously reported that MMP2 immunoexpression was significantly higher in the lung cancer group than among the healthy control group." (PMID 31921636, 2019). "The four lung cancer cell lines treated with aADSC-CM exhibited a significant increase in MMP2/9 and vimentin expression and a decrease in E-cadherin expression." (PMID 31196220, 2019). "Higher levels and activity of MMP2 and MMP9 have a significant association with the TNM stage of lung cancer and poor clinical evolution of patients with lung cancer." (PMID 30867003, 2019). "As an important cytokine, IL-6 has been observed to regulate EMT in cancers; therefore, we performed western blotting to detect MMP2/9, E-cadherin and vimentin expression in lung cancer cells treated with ADSC-CM or aADSC-CM." (PMID 31196220, 2019). "In highly metastatic lung cancer cell lines, fucoidan (F. vesiculosus) showed an inhibitory effect on the migration and invasion by reducing the expression of MMP-2 in vitro." (PMID 30621045, 2019). "In contrast, in A549 lung cancer cells, MMP2 alters the expression of VEGF through the αVβ3-integrin-controlled PI3K/Akt signaling pathway." (PMID 30871059, 2019). "In lung cancer cells, migration was facilitated by AQP1 expression, linked to expression of MMP2 and MMP9." (PMID 29922644, 2018). "It has been reported that curcumin has also inhibited the invasion of the A549 lung cancer in MT1-MMP/MMP-2 pathway." (PMID 29642589, 2018). "We also showed that HMGB1 promoted lung cancer invasion and metastasis by upregulating the expression and activity of MMP-2 in an NF-κB-dependent manner." (PMID 29850505, 2018). "Increased TRPM7 expression was associated with enhanced SOX2, KLF4, and CD133, Hsp90α, uPA, and MMP2 expression in lung cancer cells." (PMID 30477473, 2018). "Together, the findings from in vitro and in vivo analyses and from lung cancer patient samples demonstrate the sufficient and necessary roles of PLOD3, MMP-2/9, and uPA in promoting lung cancer metastasis." (PMID 30442941, 2018). "For example, MMP9 enhances CD44 cleavage and shedding, and CD44-mediated cell migration in glioblastoma xenograft cells, while CD44 regulates hyaluronan-dependent MMP2 secretion and tumor invasiveness in human lung carcinoma cells." (PMID 30002682, 2018).
lung carcinoma (continued). "The matrix metalloproteinase-2 (MMP-2) expression and activity were upregulated after treatment with HMGB1, while the upregulated expression of MMP-2 stimulated by HMGB1 in lung cancer cells was significantly reduced with the blockage of si-p65." (PMID 29850505, 2018). "Future work is necessary to determine the extent of the role of lnc‐MMP2‐2 in lung cancer pathophysiology." (PMID 30256540, 2018). "MMPs (-2 and -9) play an important part in tumor development and angiogenesis, which suggests that creating potent MMP-2 and -9 inhibitors, should be an important goal in lung cancer therapy." (PMID 29679218, 2018). "The results revealed that levels of MMP-2 were robust in discriminating patients with lung cancer form benign diseases with an area under the curves (AUC) value of 0.7536 (95% CI, 0.6512–0.8561)." (PMID 29113325, 2017). "The levels of MMP-2 in BALF from 48 lung cancer patients were analyzed according to tumor histology." (PMID 29113325, 2017). "LIN28A knockdown suppressed both migration and invasion, indicating that curcumin inhibits MMP2/9 expression via suppression of LIN28A in lung cancer cells." (PMID 28587210, 2017). "We have also observed that Mmp2 is the main gelatinase secreted by H157 lung cancer cell line after TGF-β treatment in NSCLC." (PMID 28767724, 2017). "MMP-2 holds a role in lung cancer angiogenesis mediated by vascular endothelial growth factor expression and also in the invasive behavior of tumor cells, as for MMP-7." (PMID 29207990, 2017). "Still, although in this study the involved mediators remained elusive, at least a link between IGF-I receptor activity and MMP2 mRNA and protein expression was described in murine lung cancer cells." (PMID 28928383, 2017). "The percentage of MMP-2 positive cells in lung cancer patients was significant higher than that of benign group (65.2% ± 4.9% versus 19.5 ± 3.8%, P < 0.0001)." (PMID 29113325, 2017). "Comparing lung cancer patients with benign group, the best cutoff level of MMP-2 in BALF for SCC, ADC, and SCLC were 1.794 ng/ml, 1.643 ng/ml, and 0.906 ng/ml, respectively." (PMID 29113325, 2017). "Our results indicate that curcumin treatment induces miR-98 expression and suppresses lung cancer invasion and migration by decreasing the levels of MMP2 and MMP9." (PMID 28587210, 2017). "EAME also successfully suppressed the proliferation of lung cancer cells via decreasing the expression of MMP-2/9." (PMID 29233192, 2017). "With this cut-off value, MMP-2 had a sensitivity of 75.0% and a specificity of 62.5%, to identify a patient with lung cancer." (PMID 29113325, 2017). "Our study showed that CAFs upregulated the expression of both VEGF and MMP-2, suggesting that CAFs promoted lung cancer cell metastasis by modulating metastasis-related genes." (PMID 29100297, 2017). "Several studies have reported that celecoxib inhibits adhesion and invasion in oral cancer, gastric cancer, colon cancer, lung cancer and osteosarcoma cells through various cell signaling pathways such as NF-kB, MMP-2/9, E-cadherin, β-catenin and AKT." (PMID 29383179, 2017). "The levels of MMP-2 was detected in the Bronchial alveolar lavage fluid (BALF) of 48 lung cancer patients and 40 benign diseases." (PMID 29113325, 2017). "To clarify the inhibitory role of curcumin in the in vitro growth progression of the lung cancer cell line A549, we evaluated MMP2/9 expression." (PMID 28587210, 2017). "Then, we investigated the effect of MMP-2 overexpression or silencing on ERβ expression and aggressive lung cancer." (PMID 28915603, 2017). "ROC curve was further performed to evaluate the ability of MMP-2 in differentiating lung cancer patients from those with benign diseases." (PMID 29113325, 2017). "In this study, we found that the levels of MMP-2 was higher among patients with lung cancer than in patients with benign diseases." (PMID 29113325, 2017).
lung carcinoma (continued). "PEG10 has been reported to promote lung cancer cell migration and invasion by upregulating the expression of β-catenin, MMP-2 and MMP-9, and decreasing the expression of E-cadherin." (PMID 28193232, 2017). "Matrix metalloproteinase activation has been described in large cell lung carcinoma, where elevated CAV1 expression correlates with advanced stages of lung cancer as well as increased MMP9/MMP2 expression and activity." (PMID 29340103, 2017). "A significant higher MMP-2 levels was observed among patients with lung cancer than benign diseases (6.1 ± 1.1 ng/ml versus 2.2 ± 0.6 ng/ml, P = 0.0033)." (PMID 29113325, 2017). "The findings in this study suggested that elevated expression of MMP-2 and TIMP-2 cooperatively correlates with risk of lung cancer." (PMID 29113325, 2017). "In conclusion, we demonstrate that DP2 promotes cell motility and invasiveness of human lung carcinoma cells, which attributes to the upregulated expression of uPA/uPAR and MMP-2 and activation of FAK/integrin signaling axis via TLR2/4-mediated ERK activation." (PMID 28076322, 2017). "We analyzed the effect of reduced Nrf2 on A549 and H460 cells, two of the most aggressive lung cancer lines, for MMP-2 and MMP-9 expression." (PMID 28402268, 2017). "Specifically, activated Rac1 regulates tumor invasion of lung cancer cells by regulating gene transcription of MMP2 and MMP9." (PMID 27164951, 2016). "In another model of lung cancer, MMP2 was reported to be implicated in the VEGFA expression by the tumor cells, through the PI3K/Akt pathway, underlining the major role played by MMP2 in the angiogenic process." (PMID 26921265, 2016). "Several studies have reported that celecoxib inhibits adhesion and invasion in gastric cancer, oral cancer, lung cancer, colon cancer and osteosarcoma cells through multiple cell signaling pathways such as NF-kB, MMP-2/9, E-cadherin, β-catenin and Akt/PKB." (PMID 27074576, 2016). "Trans-FA treatment inhibited the migration and invasion of lung cancer cells and concurrently attenuated the activities of both MMP-2 and MMP-9." (PMID 27733866, 2016). "MMP2 and MMP9 are associated with lung cancer and can be secreted by cancer cells resulting in invasion and metastasis." (PMID 26759080, 2016). "Liao and colleagues also demonstrated the inhibitory effect of curcumin in MMP-2 expression on lung cancer cells due to downregulation of the expression of glucose transporter 1 (GLUT-1) and MT1-MMP." (PMID 27834913, 2016). "MMPs, E-cadherin, and N-cadherin are well-known regulators of the migration and invasion of cancer cells, and MMP-2 is the most highly expressed MMP in lung cancer." (PMID 27995049, 2016). "Compared to COPD patients, insignificant change in the levels of MMP-9 and MMP-2 were observed in the serum samples of lung cancer patients." (PMID 27811960, 2016). "The authors have demonstrated that curcumin reduces lung cancer cell metastasis through inhibition of MMP-2 and MMP-9 expression mainly by downregulation of Rac1/PAK1." (PMID 27834913, 2016). "In summary, miR-129 suppressed lung cancer cell proliferation by arresting cell cycle at G2/M phase through inactivation of CDK1 by Wee1, and reduced cell migration and invasion in lung cancer through controlling the protein levels of NF-κB and MMP-2." (PMID 26081366, 2015). "An 8-marker model was developed (TFPI, MDK, OPN, MMP2, TIMP1, CEA, CYFRA 21–1, SCC) which accurately distinguished subjects with lung cancer (n = 50) from high risk smokers (n = 50) in an independent validation study (AUC = 0.775)." (PMID 26279647, 2015). "EFEMP1 is associated with decreased MMP-2 and MMP-7 levels in lung cancer and MMP-2 and MMP-9 levels in endometrial carcinoma, which are also observed in highly metastasizing and rapidly expanding tumors." (PMID 25987128, 2015). "Fibronectin up-regulates COX-2 expression and PGE2 production to enhance MMP-2 activity in rhabdomyosarcoma and promote lung carcinoma cell proliferation." (PMID 25595899, 2015).
lung carcinoma (continued). "We conducted a meta-analysis, using a comprehensive strategy based on the logistic regression and a model-free approach, to derive a more precise estimation of the relationship between MMP1, MMP2, MMP9 and MMP13 polymorphisms with lung cancer risk." (PMID 26198673, 2015). "Specifically, activated RhoA regulates tumor invasion of lung cancer cells by regulating gene transcription of MMP2 and MMP9." (PMID 25889562, 2015). "Overexpression of miR-29b has also been reported to suppress MMP-2 level in prostate and lung cancer cells." (PMID 26404322, 2015). "In parallel, the results from real-time PCR demonstrated that ectopic expression of ΔN-HDAC6-His decreased MMP2 mRNA expression levels, suggesting that nuclear HDAC6 is able to transcriptionally regulate MMP2 expression in lung cancer cells." (PMID 26388610, 2015). "Insulin-like growth factor (IGF)-1 was previously shown to up-regulate MMP-2 production in lung cancer, whereas the interleukin (IL)-10/IL-10 receptor axis was found to down-regulate MMP-2 synthesis in prostate cancer cell line PC3 ML." (PMID 24978435, 2014). "We found that transfection with pCOX2 increased COX-2 together with MIG-7 protein, EMT, MMP-2 activity and invasion of lung cancer cells." (PMID 25004182, 2014). "Previous studies have demonstrated that COX-2 derived PGE2 activates CD44 and MMP-2, and in turn stimulates invasiveness of lung cancer cells in vitro." (PMID 25190452, 2014). "In another study, JNK 1/2 pathway modulated MMP-2 production by EGCG treatment in lung cancer cells." (PMID 25184134, 2014). "The rVP1-mediated downregulation of COX-2/PGE2 and MIG-7 led to not only attenuation of epithelial-mesenchymal transition, MMP2 activity and invasion of lung cancer cells in vitro but also decreased tumor growth and metastasis of lung cancer in xenograft mice." (PMID 25004182, 2014). "Overexpression of ILK or NF-κB p65 blocked the inhibitory effect of rVP1 on COX-2 expression to induce MIG-7, EMT and MMP2 activity as well as invasiveness of lung cancer cells." (PMID 25004182, 2014). "The −1306C genotype ratio of the MMP-2 gene has been found to be significantly higher in patients with lung cancers than in the healthy population, and this genotype is associated with an increased risk of lung cancer." (PMID 25371741, 2014). "Collectively, these results suggest that rVP1 modulates integrin β1/Akt signaling to downregulate COX-2/PGE2 that then attenuates MIG-7 protein level resulting in inhibition of the EMT, MMP-2 activity and invasion of lung cancer cells." (PMID 25004182, 2014). "The administration of MMP2/LHRH Mn3O4 NPs to the mice with orthotopic lung cancer model substantially improved the visualization of the cancer mass in the lungs." (PMID 24919932, 2014). "A significant negative correlation was found between inhibition of NM modulation of Matrigel invasion and MMP-2 secretion with lung cancer A-549 (r=−0.905)." (PMID 23563849, 2013). "In this study, we focused on the modulating effect of NM on the activities of MMP-2 and -9, TIMPs and u-PA in human lung cancer (A-549 and Calu-3) and malignant mesothelioma (MSTO-211H) cell lines." (PMID 23563849, 2013). "Overexpression of MMPs is correlated with the progression of lung cancer, and the expression of either MMP-2 or MMP-9 confers a worse prognosis in early-stage lung adenocarcinoma." (PMID 24023938, 2013). "In this study, we demonstrated that GRN163L treatment led to a moderate decrease in MMP-2 expression in A549 lung cancer cells." (PMID 23545855, 2013). "To accomplish this, we co-expressed Bmal1 and Bcl-w in lung cancer cells, and examined MMP-2 levels and cellular invasiveness." (PMID 23563360, 2013). "Another report indicated that fisetin inhibits the migration and invasion of human lung cancer A549 cells by decreasing MMP-2 and uPA expression through inactivating the ERK1/2 signaling pathway." (PMID 23940799, 2013).